VCAM1 (vascular cell adhesion molecule 1)
Diseases named in the same sentence as VCAM1 in open-access papers (continued):
Sharing a sentence is not in itself a finding about the gene and the disease.
cancer (367 papers, 1993 to 2026). A tumor composed of atypical neoplastic, often pleomorphic cells that invade other tissues. "In our analysis, PCT ≥ 0.05 ng/mL and VCAM-1 ≥ 922 ng/mL were independent risk factors for cancer incidence among PWH." (PMID 40006998, 2025). "VCAM-1 silencing inhibits cancer cell proliferation and is associated with poor prognosis in GC patients." (PMID 40927361, 2025). "Adhesion to the endothelium through CD44 has been shown to involve VCAM-1, a transmembrane glycoprotein implicated in cancer progression and metastatic dissemination in several malignancies, including breast cancer." (PMID 40890143, 2025). "So far, this review has discussed the application of VCAM-1-directed therapeutics for the selective inhibition of migration-based mechanisms underlying inflammatory cell infiltration and cancer cell metastasis." (PMID 40095109, 2025). "Nevertheless, in the context of “at risk” primary cancer patients, where the assessment strategy would be specifically targeted, the probability that VCAM-1 expression in the lungs reflects metastatic involvement is substantially increased." (PMID 39000268, 2024). "Clusters were annotated based on expression of representative marker genes, as previously reported: those included EPCAM for epithelial cells, PTPRC for CD45-positive immune cells, VCAM1 for cancer-associated fibroblasts, and VWF for endothelial cells." (PMID 39122703, 2024). "High expression of both GPNMB and VCAM-1 has been associatedwith poor prognosis in patients, indicating a need for immunotherapiestargeting these proteins on cancer cells." (PMID 37067377, 2023). "Vascular cell adhesion molecule (VCAM)-1 has been implicated in cancer cell migration in part due to its link to the Src signaling activation." (PMID 36364072, 2022). "A great amount of evidence has shown that VCAM1 is significantly implicated in the metastasis of cancer cells." (PMID 32793471, 2020). "VCAM-1 anchors metastasis-associated macrophages via α4-integrins to cancer cells, triggering Akt activation, thereby protecting cancer cells from proapoptotic cytokines, including TNF-Related Apoptosis Inducing Ligand TRAIL." (PMID 31817646, 2019). "Recent evidence suggests that VCAM-1 is closely associated with the progression of various immunological disorders and cancers, so it is a potential therapeutic target in these diseases." (PMID 31035617, 2019). "Circulating VCAM-1 levels have been found to be associated with more advanced disease in many cancers." (PMID 26881177, 2016). "Several cell adhesion molecules (CAMs), including intercellular adhesion molecule-1 (ICAM-1) and vascular cell adhesion molecule-1 (VCAM-1) have been implicated in cancer growth, and metastasis." (PMID 25156554, 2014). "Indeed, cancer associated fibroblasts are able to secrete VCAM-1 which in turns increase growth and invasion through the AKT and MAPK pathways in lung cancer cells." (PMID 40071851, 2025). "VCAM-1 may be linked to the development of cancer, and elevated concentrations of VCAM-1 have been found in the peripheral blood of patients with cancer." (PMID 40006998, 2025). "Evidence from various cancer types suggests that VCAM‐1 is associated with a poor outcome." (PMID 37641470, 2023). "Furthermore, previous research also reported that VCAM-1 tethers metastasis-associated macrophages (MAMs) to cancer cells via α4 integrin and transduces a survival signal, which can protect cancer cells from apoptosis." (PMID 36497444, 2022). "Higher VCAM-1 expression was, for example, associated with higher eosinophil infiltration into the inflamed lungs of asthmatic patients, rejection of liver allografts, the severity of RA, and cancer progression." (PMID 35463298, 2022). "VCAM‐1 expression is reported to be closely implicated in the metastasis of many cancer cells." (PMID 34427969, 2021). "Expression of VCAM-1 is finely associated with cancer metastasis in several cancers." (PMID 33473259, 2020).
cancer (continued). "The expression of VCAM-1 is associated with the activation of inflammatory cytokines, such as TNFα and ROS, and is relevant to the progression of several immunological disorders and cancers." (PMID 32719746, 2020). "Besides, VCAM-1 primes the metastatic cancer cells to bind to metastasis-associated macrophages via counter-receptor α4-integrins to ensure their survival, thereby leading to the formation of metastatic lesions." (PMID 32546174, 2020). "VCAM-1 expression seems to be closely implicated in the metastasis of various cancer cells." (PMID 29614819, 2018). "Interestingly, Vcam1, Sele, and Pdpn could potentially associate with genes found in the cancer cell transcriptome, such as Itga4 and Lgal3bp." (PMID 37686421, 2023). "This gene encodes vascular cell adhesion molecule-1, whose expression is specific for epithelial cells, but under such conditions as high level inflammation or chronic diseases, its expression is also found on the surfaces of other cell types, including cancer cells." (PMID 35742950, 2022). "The remainder of this review goes on to summarise the existing evidence and current developments supporting the anti-colitic and anti-cancer potential of several approved and novel therapeutics that target VCAM-1 in colorectal pathologies." (PMID 40095109, 2025). "Inflammation also drove lymphatic permeability and invasion by cancer cells when VCAM-1 was induced in lymphatic endothelial cells." (PMID 40071851, 2025). "Naturally, therapeutic blockade of inflammatory cell infiltration and cancer cell metastasis via VCAM-1 has been posed as an intriguing strategy for a range of inflammatory and cancerous pathologies, including colorectal diseases." (PMID 40095109, 2025). "On the other hand, studies have reported areas of high microvessel density that correlated with high VCAM-1 expression in various cancers." (PMID 40071851, 2025). "Considering the mounting evidence of VCAM-1 involvement in angiogenesis across several cancer pathologies, it would be expected that aberrant VCAM-1 expression would serve a similar function in CRC." (PMID 40095109, 2025). "Existing reviews have reported the therapeutic effects of VCAM-1 in inflammation and cancer separately, but this is the first to definitively explore the common roles of VCAM-1 across both disease contexts." (PMID 40095109, 2025). "We found that cancer cells and CAFs decreased expression by ECs of VCAM‐1 leukocyte adhesion protein, which is crucial for immune infiltration." (PMID 40348600, 2025). "The unique α4 integrin property of VCAM-1 enables its interaction with VCAM-1 on cancer cell surfaces, making it an attractive carrier for treating lung metastasis." (PMID 40528159, 2025). "VCAM-1 overexpression has been reported in several cancer pathologies—including breast, ovarian, gastric, and pancreatic cancer." (PMID 40095109, 2025). "We observed a slight increase in circulating vascular cell adhesion molecule-1 (VCAM-1) following regular exercise in patients with cancer." (PMID 41583457, 2025). "The VCAM-1 protein has also been noted for its functional involvement in cancer metastasis and drug resistance to conventional chemotherapeutics." (PMID 40095109, 2025). "Although the anti-inflammatory and anti-cancer facets of VCAM-1 antagonisation have been examined separately, there is yet to be a review that explicitly addresses the functional interrelationship between these mechanisms." (PMID 40095109, 2025). "Using TCGA database, our analysis of VCAM-1 expression patterns in various cancer and normal tissues revealed the notable upregulation of VCAM-1 levels in most cancer types." (PMID 40927361, 2025). "Though VCAM-1 is generally described as an endothelial protein, several varieties of transformed cancer cells also aberrantly overexpress VCAM-1 on their surface." (PMID 40095109, 2025).
cancer (continued). "In contrast, VCAM1 cell surface expression was only detected in mesenchymal cSCCs, discarding this marker for identifying early epithelial plastic cancer cells." (PMID 39075581, 2024). "Lung metastasis-associated macrophages promote survival signals in breast cancer cells (BCCs) by binding to VCAM-1 on cancer cells." (PMID 39402303, 2024). "Mesothelial cells play an active role in inflammation and cancer by expressing adhesion molecules (e.g., P selectin, VCAM-1, and ICAM) and by producing and responding to cytokines and chemokines." (PMID 39402303, 2024). "Overexpression of VCAM-1 led to an increased monocyte infiltration and promoted interaction between cancer cells and TAMs." (PMID 39596815, 2024). "The cross-talk between cancer cells and BMEC is stimulated by the expression of cellular adhesion molecules (E-selectin, VCAM-1) on cancer cells and degradation of the BBB by matrix metalloproteinases." (PMID 39175471, 2024). "In contrast with these studies, another line of evidence indicated that VCAM-1 is overexpressed in several types of tumors, including renal, gastric, and ovarian cancers, where it is likely correlated with angiogenesis, cancer invasion, and metastasis." (PMID 39596815, 2024). "Analyses targeting post-translational modifications in VCAM-1 or its ligands are especially important for understanding how these modifications impact VCAM-1 function in health and disease (e.g., during cancer or inflammation)." (PMID 39769411, 2024). "Alternatively, macrophagemembrane-based biomimetic nanoparticles are widely used to expressintegrins (e.g., α4) on the surface of their membranes, enablingbinding to vascular cell adhesion molecule-1 (VCAM-1) on the surfaceof cancer cells." (PMID 38848540, 2024). "The release of soluble VCAM-1 was reported to enhance the growth and invasion of cancer cells through the activation of the α4β1 integrin." (PMID 39596815, 2024). "Elevated levels of TNF in OC ascites have also been associated with elevated expression of the adhesion molecule VCAM‐1 on mesothelial cells, thereby enabling cancer‐mesothelial cell interactions leading to cancer cell attachment and invasion." (PMID 38566518, 2024). "Vascular cell adhesion protein 1 (VCAM-1, CD106) is a glycoprotein involved in angiogenesis and cancer metastasis." (PMID 39201395, 2024). "VCAM1, expressed by cancer cells, restricts iNKT cell motility and inhibits their antigen scanning and activation by DCs via reducing CDC42 expression." (PMID 38332012, 2024). "After actively targeting vascular cell adhesion molecule-1 (VCAM-1) in cancer cells mediated by macrophage membrane coating, M@GOx-CAT@CuS NPs released GOx and CAT under near-infrared irradiation." (PMID 38840654, 2024). "In this study, we found that TBMS1 treatment lowered VEC expression of cancer adhesion molecules (ICAM-1 and VCAM-1), and reduced cancer cells adhesion on VEC monolayers." (PMID 38230220, 2024). "The surface of endothelial are covered with adhesion molecules, including ICAM-1 and VCAM-1, which mediate the adhesion and extravasation of cancer cells." (PMID 38230220, 2024). "Specifically, our results showed an upregulation of Cldn7, Krt7, Axl, Tnc, Itgav, Itgb3, and Vcam1 in EpCAMhigh and EpCAMlow cancer cells relative to levels in full epithelial cancer cells." (PMID 39075581, 2024). "Various adhesion molecules mediate the transendothelial migration of cancer cells, including activated integrins of cancer cells, such as α4β1 binding to endothelium ligand VCAM-1 and αLβ1 binding to LCAM-1." (PMID 36672259, 2023). "Bisacurone inhibits TNF-α-mediated soluble vascular cell adhesion molecule-1 (VCAM-1) expression in inflammatory monocytes and cancer cells." (PMID 37298318, 2023). "Serum elevations of vascular cell adhesion molecule 1 (VCAM-1) and E-Selectin (cancer-promoting) were noted in SSc and were associated with disease severity." (PMID 37681925, 2023).
cancer (continued). "Reactivated cancer cells express VCAM-1 with the recruitment of osteoclastic precursors and the release of several factors, such as PTHrP." (PMID 36900309, 2023). "VCAM-1 is an endothelial cell adhesion molecule, which is shown to be involved in inflammation and cancer." (PMID 37179352, 2023). "Taken together, the specific binding to membrane-bound GPNMB andVCAM-1 by each binder warrants further development as DbTEs for immunotherapyagainst GNNMB and VCAM-1 overexpressing cancers." (PMID 37067377, 2023). "This is the first report of GPNMB or VCAM-1-specifichuman VH domain antibodies as candidates for cancer immunotherapy." (PMID 37067377, 2023). "VCAM1, a member of the IgG immunoglobulin family, plays a well-known role in cancer development and progression." (PMID 37568580, 2023). "Overexpression of vascular cell adhesion molecule 1 (VCAM1) on 4T1 cancer cell membranes exhibits high affinity for very late antigen-4 (VLA-4) on lymphocytes, monocytes, and eosinophils." (PMID 38276484, 2023). "GPNMB and VCAM-1 are bothpotentially powerful targets in the treatmentof several types of cancer because of their high expression and functionin metastasis." (PMID 37067377, 2023). "α4 and β1 integrins interact with VCAM-1 on cancer cell membranes, allowing selective interaction with target cancer cells." (PMID 37376125, 2023). "Similar lysis was also found in GPNMB positive sk-mel-28cancer cells and VCAM-1 positive HuT-78 cancer cells, respectively." (PMID 37067377, 2023). "Triggering the PI3K/Akt survival pathway through engaging vascular cell adhesion molecule-1 (VCAM1) and the secretion of cytokines and chemokines can increase the survival of cancer cells." (PMID 37509382, 2023). "Overall, we identified TNFα as a potential angiogenic stimulus driving the pre-metastatic niche for homing metastatic cancer cells through VCAM-1 upregulation." (PMID 36290384, 2022). "Given that EGFR and CD24 are already proposed and in the process of being therapeutically exploited, we now propose VCAM1 as a novel biomarker and target for cancer-specific stratified immunotherapy." (PMID 36221114, 2022). "Recent data indicate a relationship between VCAM-1 expression and cancer metastasis and angiogenesis." (PMID 35740491, 2022). "Adhesion molecules such as VCAM1 promote cancer metastasis, or in the case of blood cancers, extravasation, by allowing cancer cells to exit the bloodstream and integrate with healthy tissues throughout the body." (PMID 36873459, 2022). "Meanwhile, this protumor function of VCAM-1 can be eliminated by the α4-integrin blockade and delay cancer bone metastasis." (PMID 36497444, 2022). "This revealed that expression of several cancer-associated proteins, including GM-CSF, CCL20 and VCAM1, was strongly dependent on MALT1 catalytic activity in PC3 cells." (PMID 36009554, 2022). "The macrophage membranes were isolated from RAW264.7 cells with high expression of α4 and β1 integrins, which can specifically bind to VCAM-1 on cancer cells." (PMID 36575429, 2022). "Several studies have reported that the cell surface molecules (Sialyl-Lewis A/X and integrin α4β1) on cancer cells and adhesion molecules (E-selectin and VCAM-1) on the surface of liver endothelial cells promote liver metastasis through specific binding." (PMID 35039535, 2022). "It has been shown that preferential binding between adhesion molecules, such as integrin α4β1 and vascular cell adhesion molecule 1 (VCAM-1), enhances the attachment between cancer cells and endothelial cells." (PMID 35039535, 2022). "Lastly, VCAM-1/VLA-4 as therapeutic clinical targets has also been supported by a myriad of studies in other cancer types." (PMID 36497180, 2022). "Integrin α4 and integrin β1 are usually detected in macrophage membranes because they can actively bind to vascular cell adhesion molecule-1 of cancer cells or inflamed endothelium." (PMID 36575429, 2022).
cancer (continued). "In endothelial cells, IL-18 upregulates VCAM-1, which enhances metastatic implantation and the spread of cancer cells." (PMID 36678726, 2022). "Preoperative plasma VCAM-1 was independently associated with recurrence-free survival (RFS), cancer-specific survival (CSS), and overall survival (OS) in pre- and postoperative multivariable models." (PMID 35347517, 2022). "This was due to the interaction between α4β1 integrin and VCAM-1 in cancer cells that contributed to specific metastasis-targeting toward cancer metastasis." (PMID 35677298, 2022). "Liposomes carrying antitumor drugs (emtansine or doxorubicin) were hybridized with macrophage or NK cell vesicles for targeted cancer therapy through interactions of α4β1/VCAM-1 and NKG2-D and its ligands, respectively." (PMID 35874757, 2022). "In the following review, we provide a survey of available literature that supports the functional contribution of VCAM-1/VLA-4 interaction in cancer and ongoing attempts to exploit this signaling axis for clinical therapeutic purposes." (PMID 36497180, 2022). "VCAM-1 is known to be induced by TLRs and proinflammatory cytokines and is related to cancer progression and metastasis of several cancer types." (PMID 34436224, 2021). "VCAM1 is involved in the development of some malignant tumors, and overexpression of VCAM1 facilitates metastasis by promoting epithelial-mesenchymal transformation and transendothelial migration by enhancing pseudopodia formation." (PMID 34526555, 2021). "In vitro and in vivo cancer models have shown that active Notch regulates the expression of adhesion molecule VCAM1 ensuring cancer cell migration across capillaries and blood vessels." (PMID 33430387, 2021). "Intercellular and vascular adhesion molecules (ICAM-1 and VCAM-1) play an important role in cancer progression; however, data in the literature are often contradictory." (PMID 34680113, 2021). "This increases endothelial VCAM1 expression, which facilitates cancer cell homing and the formation of secondary tumors." (PMID 34073394, 2021). "VCAM-1 can tether macrophages to cancer cells via counter-receptor α4β1-integrins, and we found that macrophages and fibroblasts in the SPTCL microenvironment highly expressed ITGA4 and ITGB1, which constitute α4β1-integrins." (PMID 33816243, 2021). "Clustering of VCAM-1 on the cell surface, acting through Ezrin, triggers Akt activation and protects cancer cells from proapoptotic cytokines such as the TNF-related apoptosis-inducing ligand (TRAIL)." (PMID 33816243, 2021). "TAMs support the survival of cancer cells in the circulation by the interaction of α4 integrin with vascular cell adhesion molecule-1 (VCAM-1) on the surface of cancer cells." (PMID 33919517, 2021). "High expression of CXCR4 in NSCLC cells have been shown to promote cancer cells-mediated osteoclast differentiation through secreting VCAM1." (PMID 34136487, 2021). "Noteworthily, a specific formulation of VCAM-1-targeted Lp used to block site-specific chemokine-related inflammatory processes in vascular diseases and cancer metastasis has been successfully developed by our group." (PMID 33763173, 2021). "VCAM-1, in particular, has been presented as a major biomarker of tumorigenesis in many types of cancers, further reinforcing its early biomarker status." (PMID 34504791, 2021). "Cell adhesion molecules, such as ICAM-1 and VCAM-1, are involved in cancer growth, migration from primary sites to distant organs, and adhesion to ECs." (PMID 32466580, 2020). "Upon the binding of aptamers to their respective VCAM-1 and IL4Rα receptors, they block their biological function and thus promote cancer cell deaths." (PMID 32751068, 2020). "The adhesion of NK cell variants to cancer endothelium shows similarities to that of CD8 T cells, starting with selectin-induced rolling, followed by VCAM-1-VLA-4 mediated adhesion and transmigration." (PMID 33262763, 2020).